CARINH (colitis associated IRF1 antisense regulator of intestinal homeostasis)
Synonyms: formerly C5orf56; IRF1-AS1
Gene: Long non-coding RNA gene on chromosome 5 (132,410,636 to 132,488,702, forward strand). Ensembl gene ENSG00000197536.
Diseases named in the same sentence as CARINH in open-access papers:
CARINH is named in the same sentence as 23 diseases in open-access papers, as found by Europe PMC text mining. Sharing a sentence is not in itself a finding about the gene and the disease. The quoted sentences say what the papers report.
colitis (5 papers, 2023 to 2025). Inflammation of the colon. "lncRNA Colitis Associated IRF1 antisense Regulator of INtestinal Homeostasis (CARINH), also known as C5ORF56 and ISR8/IRF1-AS1, is located on the opposite strand of the interferon regulatory factor 1 (IRF1) gene, in the antisense direction." (PMID 39773901, 2025). "Analysis of RNA sequencing data from 1821 mucosal biopsies from the Mount Sinai Crohn’s and Colitis Registry identified CARINH as a hub gene within a module linked to inflammation and disease severity." (PMID 41283334, 2025). "In this context, this review is focused on the lncRNA Colitis Associated IRF1 antisense Regulator of Intestinal Homeostasis (CARINH), a lncRNA conserved in mice that plays important regulatory roles in interferon-driven innate immunity and various cancers." (PMID 41283334, 2025). "CARINH (Colitis Associated IRF1 antisense Regulator of Intestinal Homeostasis) is another mammal-conserved lncRNA, which is localized close to the 3’ end of the coding gene IRF1 in human and mice." (PMID 39036601, 2024). "Since this lncRNA interacts with gut microbiota and controls intestinal inflammation, we named it Colitis Associated IRF1 antisense Regulator of Intestinal Homeostasis (CARINH)." (PMID 37055591, 2023). "Murine Carinh is upregulated in myeloid cells sorted from colitis colons than healthy ones, and human CARINH levels are increased in gut specimens from inflammatory bowel disease (IBD) patients than control biopsy tissues." (PMID 39036601, 2024). "These phenotypes imply an increase in the severity of colitis in the colons of the DSS- or TNBS- treated CarinhKO mice, lending support for the clinical findings from human genetics studies, which have linked CARINH with IBD pathogenesis." (PMID 37055591, 2023).
inflammatory bowel disease (4 papers, 2024 to 2025). A spectrum of small and large bowel inflammatory diseases of unknown etiology. "Currently, the role of CARINH has been implicated in several immune-driven conditions, including inflammatory bowel disease (IBD), psoriasis, asthma, and Chronic Obstructive Pulmonary Disease (COPD) as well as cardiometabolic disorders." (PMID 41283334, 2025). "The presence of a mouse ortholog to CARINH presents a unique opportunity to explore its functions in vivo using Carinh knock-out mice, as demonstrated in inflammatory bowel disease and viral infection." (PMID 41283334, 2025). "Elevated expression is particularly evident in the lung, spleen, colon, and whole blood, consistent with the reported role of CARINH in antiviral responses to respiratory infections and in the pathogenesis of inflammatory bowel disease." (PMID 41283334, 2025). "Our studies of CARINH corroborate other reports that this lncRNA is an IFN-responsive gene in models of cancer and inflammatory bowel disease." (PMID 39773901, 2025).
juvenile idiopathic arthritis (2 papers, 2025). Juvenile idiopathic arthritis (JIA) is the term used to describe a group of inflammatory articular disorders of unknown cause that begin before the age of 16 and last over 6 weeks. "Additionally, there is a broader connection between CARINH and loci with autoimmune diseases, such as juvenile idiopathic arthritis." (PMID 41283334, 2025).
viral infection (2 papers, 2025). "The decreased expression of IRF1 resulting from targeting CARINH with antisense oligonucleotides or genetically in Carinh−/− mice resulted in elevated susceptibility to viral infection." (PMID 39773901, 2025). "Due to its effects on the IFN-driven immunity, CARINH has been implicated viral infections, immune and auto-immune diseases, and cardiometabolic disorders." (PMID 41283334, 2025). "Studies in HeLa cells in the context of viral infection suggested that the promoter region of CARINH has potential enhancer activity, boosting the expression of IRF1 independently of CARINH expression levels." (PMID 39773901, 2025). "Stimulated by interferons and viral infections, CARINH stands out as a key player in the body’s antiviral defense mechanisms." (PMID 41283334, 2025). "In this review, we have highlighted CARINH, a conserved long noncoding RNA that is upregulated upon viral infection, as well as upon stimulation with IFNs." (PMID 41283334, 2025). "Targeted depletion of CARINH or its mouse ortholog Carinh in macrophages reduces the expression of IRF1/Irf1 and their associated target gene networks, increasing susceptibility to viral infection." (PMID 39773901, 2025). "Collectively, our data provide insight into the role of CARINH and its murine ortholog Carinh in regulating the IFN transcriptional program upon viral infection." (PMID 39773901, 2025). "Taken together, these data identify CARINH and its proximal coding gene IRF1 as a putative cis-acting lncRNA-mRNA pair induced by viral infection in humans." (PMID 39773901, 2025). "Together, our results suggest a role of CARINH in regulating IRF1 expression and coordinating the expression of ISGs required to limit viral infection in human innate immune cells." (PMID 39773901, 2025). "CARINH and IRF1 are coordinately increased in the circulation of patients infected with human metapneumovirus, influenza A virus, or SARS-CoV-2, and in macrophages in response to viral infection or TLR3 agonist treatment." (PMID 39773901, 2025).
bladder cancer (1 paper, 2025). "Building on the broader association with cancer, a study of bladder cancer investigated CARINH as part of an epithelial-to-mesenchymal transition (EMT)-related lncRNA signature linked to cancer prognosis and disease progression." (PMID 41283334, 2025). "This leaves it unclear whether CARINH has a direct causal role in bladder cancer progression." (PMID 41283334, 2025). "Consequently, the clinical significance of CARINH in relation to altering EMT in bladder cancer remains preliminary and necessitates direct experimental investigation." (PMID 41283334, 2025).
breast carcinoma (1 paper, 2025). "While the observations in these two patient studies point to a putative regulatory role for CARINH in breast cancer, further in vitro and in vivo functional studies are essential to validate its causal influence and to uncover the mechanisms through which CARINH impacts carcinogenesis." (PMID 41283334, 2025).
esophageal cancer (1 paper, 2025). A primary or metastatic malignant neoplasm involving the esophagus. "In esophageal cancer, RNA–protein interaction assays have shown that CARINH interacts with ILF3 (Interleukin Enhancer Binding Factor 3) and DHX9 (DExH-Box Helicase 9) to control the expression of the CARINH and IRF1 locus via a feedforward mechanism." (PMID 39773901, 2025).
esophageal squamous cell carcinoma (1 paper, 2025). Esophageal squamous cell carcinoma (ESCC) is a type of esophageal carcinoma (EC) that can affect any part of the esophagus, but is usually located in the upper or middle third. "The first direct evidence linking CARINH to cancer was observed in esophageal cancer, specifically within esophageal squamous cell carcinoma (ESCC)." (PMID 41283334, 2025).
influenza (1 paper, 2025). An acute viral infection of the respiratory tract, occurring in isolated cases, in epidemics, or in pandemics; it is caused by serologically different strains of viruses (influenzaviruses) designated A, B, and C, has a 3-day incubation period, and usually lasts for 3 to 10 days. "Of our top candidate cis-acting lncRNAs, we found that LINC02422 and CARINH were significantly up-regulated in macrophages upon infection with any of the influenza strains, whereas GSEC remained unresponsive." (PMID 39773901, 2025).
leukemia (1 paper, 2025). A malignant (clonal) hematologic disorder, involving hematopoietic stem cells and characterized by the presence of primitive or atypical myeloid or lymphoid cells in the bone marrow and the blood. "Studies in leukemia suggest that CARINH interacts with several miRNAs, including miR-31, miR-144, miR-194, miR-216a, miR-375, and miR-490, thereby influencing the translation of their downstream targets." (PMID 41283334, 2025).
psoriasis (1 paper, 2025). An autoimmune condition characterized by red, well-delineated plaques with silvery scales that are usually on the extensor surfaces and scalp. "Among 13 loci encompassing 653 SNPs shared between psoriasis and cardiovascular traits, the 5q31.1 locus, which includes CARINH, emerged as particularly significant in these associations." (PMID 41283334, 2025). "In the context of psoriasis, CARINH has been associated with therapeutic responses." (PMID 41283334, 2025).
cancer (3 papers, 2021 to 2025). A tumor composed of atypical neoplastic, often pleomorphic cells that invade other tissues. "As expected, given its role in regulating IRF1 expression and the IFN response, CARINH is implicated in various cancers." (PMID 41283334, 2025). "Interestingly, among the miRDB-predicted miRNA interactions with CARINH were several miRNAs that were linked to innate immunity and cancer biology, such as miR-342-5p, miR-423-5p, miR-766-3p, and miR-4516, among many others." (PMID 41283334, 2025). "In this review, we delve into CARINH’s pivotal function in modulating interferon responses and influencing cancer development, with a focus on the molecular pathways that regulate its expression and contribute to its diverse roles." (PMID 41283334, 2025). "In cancer research, CARINH has been found to interact with transcriptional co-activators DHX9, ILF3 to regulate the expression of IRF1, with its loss contributing to tumor progression." (PMID 41283334, 2025). "CARINH is an intriguing long noncoding RNA whose unique regulatory functions intersect the seemingly distinct processes of innate immunity and cancer development." (PMID 41283334, 2025). "Furthermore, alterations in CARINH expression have been connected to cancer progression, highlighting its dual role in immune response and tumor suppression." (PMID 41283334, 2025). "Patients’ studies further suggest that CARINH is included in several lncRNA signatures that may be predictive of clinical outcomes, highlighting its potential as a future biomarker in cancer." (PMID 41283334, 2025). "Additionally, CARINH is part of an extensive ceRNA network that is involved in various cancer-related pathways, such as metastasis and cell proliferation." (PMID 41283334, 2025). "Further in vitro and in vivo studies are necessary to confirm this causal role and to uncover the mechanisms through which rs2522057 may regulate IRF1, RAD50, and SCL22A5 expression via CARINH, ultimately affecting cancer development." (PMID 41283334, 2025). "However, the precise link between elevated levels of CARINH and either poor or favorable prognosis remains unclear and is likely cancer dependent." (PMID 41283334, 2025).
tumor (3 papers, 2025). "Conversely, CARINH overexpression suppressed proliferation, impaired colony formation, and promoted apoptosis in vitro, while tumor weights and volumes of in vivo xenografts were reduced when compared to controls." (PMID 41283334, 2025). "Loss-of-function experiments using short hairpin RNAs (shRNAs) revealed that knocking down CARINH promoted colony formation of KYSE cells, reduced cisplatin-induced apoptosis in vitro, and led to increased tumor growth in xenografts of subcutaneously injected KYSE30 cells." (PMID 41283334, 2025). "Clinically, CARINH expression was significantly reduced in ESCC tumors compared to healthy esophageal tissues, and low expression correlated with poor clinical outcomes, consistent with a tumor-suppressive function." (PMID 41283334, 2025).
infection (2 papers, 2025). The state of being infected such as from the introduction of a foreign agent such as serum, vaccine, antigenic substance or organism. "Knockdown of CARINH significantly increased the percentage of IAV-infected macrophages compared with GapCTRL treatment, leading to a doubling of infection and to decreased cell viability." (PMID 39773901, 2025). "CARINH has been shown to be induced by IFN in esophageal squamous cell carcinoma and HeLa cells, and deletion of its promoter region leads to decreased cell survival upon infection with encephalomyocarditis virus." (PMID 39773901, 2025).
bacterial infection (1 paper, 2025). "Here, we show an impaired expression of IFNγ in human macrophages treated with GapCARINH and in mice depleted for Carinh upon viral stimulus, suggesting a potential function for CARINH upon bacterial infection." (PMID 39773901, 2025).
CARINH also shares sentences with these, for which no sentence is quoted: asthma (2 papers); chronic obstructive pulmonary disease (2); Crohn disease (2); Allergy (1); autoimmune disease (1); malaria (1); metastatic tumor (1); respiratory infections (1).